SIRT1 (sirtuin 1)
Diseases named in the same sentence as SIRT1 in open-access papers (continued):
Sharing a sentence is not in itself a finding about the gene and the disease.
colon carcinoma (continued). "Our study is the first to confirm that propofol could inhibit the stemness and EMT of colon cancer cells at least partially through, SIRT1, and the Wnt and PI3K/AKT/mTOR signaling pathways." (PMID 37490168, 2023). "Notably, high expression levels of SIRT1 have a correlation with shorter overall survival and disease‐specific survival in colon cancer patients." (PMID 34826187, 2022). "We first investigated the role of SIRT1 in proliferation and growth of human colon cancer cells." (PMID 34826187, 2022). "SIRT1 is highly expressed in human colon cancer (e.g., HCT‐116) cells at the basal levels." (PMID 34826187, 2022). "Recent studies have shown that SIRT1 is overexpressed in CRC tissues as well as several colon cancer cell lines, suggesting that this enzyme may function as a tumor promoter." (PMID 34826187, 2022). "Thus, phosphorylation of SIRT1 at the serine 47 residue has been considered to have a distinctive role in the colon cancer progression." (PMID 34826187, 2022). "This prompted us to investigate a role of phospho‐SIRT1 in the context of colon cancer progression." (PMID 34826187, 2022). "Furthermore, the mRNA levels of c‐Myc, Bmi‐1, and Sox‐2, which are considered to be oncogenic in the colon cancer, were reduced by SIRT1 siRNA." (PMID 34826187, 2022). "As resveratrol and pterostibenes, the piceatannol and its O-methyl metabolite isorhapontigenin have demonstrated a strong capacity to upregulate SIRT1 mRNA and SIRT1 protein in monocytes cells, and have shown a strong effect on miRNAs expression in melanoma and colon cancer." (PMID 34942997, 2021). "On the contrary, in human colon cancer Sirt1 is often overexpressed, especially in advanced stages." (PMID 30304806, 2018). "SIRT1 overexpression inhibited human colon cancer cell proliferation." (PMID 29752439, 2018). "Our findings unveil that SIRT1 dependent autophagy pathway could affect 5-Fu chemoresistance in colon cancer cells, which was modulated by H19/miR-194-5p axis." (PMID 30451820, 2018). "Furthermore, Yamakuchi and colleagues provide evidences that SIRT1 can be recognized and targeted by miR-34a and miR-34c in colon cancer cells." (PMID 30533999, 2018). "In conclusion, these results support SIRT1 involvement in colon cancer development in women." (PMID 30410074, 2018). "SIRT1 deacetylates β-catenin, suppresses its ability to activate transcription, drives cell proliferation and inhibits intestinal tumour formation in patients with colon cancer." (PMID 27793039, 2016). "SIRT1 may act as a tumor promoter or suppressor, depending on the tumor type, as its overexpression inhibits tumorigenesis in colon tumors and ovarian cancer, but stimulates tumorigenesis in prostate tumors and acute myeloid leukemia." (PMID 27081083, 2016). "MiR-373 is an oncogene and can induce tumor initiation and progression in testicular germ-cell tumors by targeting tumor suppressor LATS2, and invasion and metastasis by targeting CD44, RECK, mTOR and SIRT1 in breast, colon cancer and fibrosarcoma, respectively." (PMID 26258411, 2015).
colon carcinoma (continued). "Additionally, Sirt1 has been shown to overexpress in several cancer cells, including breast, prostate, ovarian, and colon cancer cell lines." (PMID 25184156, 2014). "Moreover, SIRT1 has been suggested as a tumor suppressor in colon cancer due to its ability to deacetylate and inactivate oncogenic β- catenin." (PMID 24127549, 2013). "Moreover, other researchers have revealed that SIRT1 is highly expressed in the cytoplasm of colon cancer cell lines and increased in colon tumors compared to normal colon tissues." (PMID 23805287, 2013). "In colon cancer, SIRT1 was found to negatively regulate the oncoprotein â-catenin." (PMID 23024800, 2012). "Moreover, repression of SIRT1 in APC wild type colon cancer cells induced massive apoptosis in a FOXO4-dependent manner." (PMID 21698133, 2011). "Here we show that CR induces a two-fold increase SIRT1 expression in the intestine of rodents and that ectopic induction of SIRT1 in a β-catenin-driven mouse model of colon cancer significantly reduces tumor formation, proliferation, and animal morbidity in the absence of CR." (PMID 18414679, 2008). "When β-catenin expression was scored in these same colon cancers, a highly significant inverse correlation between the level of SIRT1 expression and nuclear β-catenin localization became apparent (p≤0.003, odds ratio 0.24 with 95% confidence interval 0.093–0.63)." (PMID 18414679, 2008). "We found that a subset of colon cancers express SIRT1 in the nucleus (47/81 cases; 58%)." (PMID 18414679, 2008). "In colon cancer, SIRT1 inhibition may be a therapeutic strategy." (PMID 39479446, 2024). "ZMIZ1 may control the fate of colon cancer cells through the SIRT1/FOXO3a axis." (PMID 38214831, 2024). "Studies have also shown that the vitamin D active substance 1α,25-dihydroxyvitamin D+3 (1,25(OH)2D3, calcitriol) can promote SIRT1 activation in colon cancer cells, and SIRT1 activators may provide new therapeutic possibilities for patients with VD deficiency or non-response to colon cancer." (PMID 39268463, 2024). "To clarify whether ZMIZ regulates autophagy, proliferation and apoptosis of colon cancer cells through SIRT1, we set up two rescue experiments in which the cells of ZMIZ1 knockdown (ZMIZ-KD) were subjected to SIRT1 knockdown (SIRT-KD) or pharmacological inhibition (SIRT1 Inhibitor) (EX527, 100 nM)." (PMID 38214831, 2024). "Since SIRT1 positively regulates expression of IL‐6 and IL‐8 that play crucial roles in proliferation of colon cancer cells, we speculate that SIRT1 may partly promote the colon cancer cell growth and migration through production of these cytokines." (PMID 34826187, 2022). "Taken together, these observations suggest that SIRT1 stabilized through phosphorylation on serine 27 exerts oncogenic effects at least partly through deacetylation‐dependent activation of Snail and subsequent transcription of IL‐6 and IL‐8 in human colon cancer cells." (PMID 34826187, 2022). "In addition, numerous studies implicate SIRT1 in tumorigenesis in various cancer types, including colon cancer and melanoma cells, but its function in most cancer cells is still under debate because of its controversial roles in tumorigenesis, which are dependent on cell type or context." (PMID 32636443, 2020). "A recent report showed that enhanced SIRT1 expression in a β-catenin-dependent mouse model of colon cancer inhibited intestinal-tumor formation, thereby indicating that the effects of SIRT1 might vary in different tumor models, and depend on the presence of appropriate downstream targets." (PMID 25424420, 2014).
colon carcinoma (continued). "Finally, down-regulation of SIRT1 in breast and colon cancer cell lines leads to re-expression of the Wnt pathway inhibitors, SFRP1 and SFRP2 (Secreted Frizzled-like Proteins 1 and 2), which are frequently inactivated in human cancers through epigenetic means, as discussed in greater detail below." (PMID 23799088, 2013). "Finally, SIRT1 protein levels were also reduced in RKO colon cancer cells and SIRT1was found to maintain silencing of TSGs including the mismatch repair gene, MLH1, for which epigenetic silencing and loss of function produces the microsatellite instability (MIN+) colon cancer phenotype." (PMID 16596166, 2006). "According to Simons (2018), SIRT1 gene polymorphism influences the risk of colon cancer in women, with the rs12778366 CC genotype being associated with a decreased risk of colorectal and colon cancer in this population, whereas no such effect has been observed in males." (PMID 40507674, 2025). "Sulindac has been shown to inhibit the migration and invasion of prostate, lung, breast and colon cancer cells by inhibiting the β-Catenin, EMT, TGFβ/miR-21, SIRT1 and AKT signaling pathways." (PMID 40371356, 2025). "First, we treated the colon cancer cell line HCT116 with increasing aspirin and EX527, a specific SIRT1 inhibitor." (PMID 38482749, 2024). "Conversely, SIRT1 and SMAD3 displayed high differential expression in LEV-treated Caco-2 cells while showing low differential expression in TCGA colon cancer tissue samples." (PMID 39110260, 2024). "Next, we confirmed the expression of RAD51C, RFC4, SIRT1, SIRT5, and SMAD3 genes in different colon cancer cell lines." (PMID 39110260, 2024). "Unexpectedly, SIRT1 levels were found almost unchanged in osteosarcoma IF1-expressing cells and significantly decreased in IF1-expressing colon carcinoma cells." (PMID 37834071, 2023). "Taken together, these results indicate that SIRT1, Wnt/β-catenin pathway and PI3K/AKT/mTOR pathway are critical to propofol mediated inhibition of colon tumor stemness and EMT in vitro." (PMID 37490168, 2023). "SIRT1 is significant in maintaining the characteristics of colon CSCs, promoting EMT, and metastasis in colon cancer cells and their stemness." (PMID 37490168, 2023). "In conclusion, this study demonstrates that reversible acetylation of HINT1 at K21 and K30 by CBP and SIRT1 modulates the capacity of HINT1 to bind to β-catenin or MITF and in turn to control tumorigenic features in colon cancer and melanoma cells." (PMID 32636443, 2020). "SIRT1/PGC1-α axis has also been correlated with chemoresistance and metabolic shift towards OXPHOS in liver metastasis of colon cancer." (PMID 26527315, 2015). "We have previously demonstrated that selective siRNA mediated knockdown of SIRT1 results in re-expression of E-Cadherin, TSG in RKO colon cancer cells." (PMID 26622943, 2015). "By activation of SIRT-1, a NAD+-dependent deacetylase, resveratrol not only induces autophagy and extends lifespan, but also suppresses colitis and colon cancer." (PMID 22053190, 2011). "Interestingly, suppression of SIRT1 by CF-EOs enhanced the acetylation of ULK1, which in turn prompted ROS-dependent autophagy in colon cancer cells." (PMID 38539819, 2024). "Schisandrin lowered SIRT1 protein expression, and there was a negative association between SIRT1 and the stimulation of SMURF2, which inhibits colon cancer cell proliferation and dissemination." (PMID 39451522, 2024). "Taken together, these findings indicate that SIRT1 could regulate the stemness and EMT of colon cancer cells, and that SIRT1 may serve as potential target for colon cancer treatment." (PMID 37490168, 2023). "SIRT1 overexpression or knockdown affected the stemness and EMT of colon cancer cells." (PMID 37490168, 2023). "Notably, SIRT1 overexpression in HCT‐116 cells and other colon cancer cell lines was predominantly observed in the cytoplasm." (PMID 34826187, 2022).
colon carcinoma (continued). "In previous studies on tumor chemotherapy drug resistance, miR-29b was found to reverse Oxa resistance of CRC cells by targeting the SIRT1/ROS/JNK pathway, moreover, it can also target FOLR1 to inhibit cell growth of colon cancer cells and increases cell sensitivity to Oxa." (PMID 32760217, 2020). "Recently, the interaction between SIRT1 and PGC-1α has attracted much attention in the study of tumorigenesis, as a SIRT1/PGC-1α-dependent increase in oxidative phosphorylation enhanced the resistance of colon cancer to chemotherapy." (PMID 27081083, 2016). "Increased SIRT1 expression greatly reduced proliferation in both colon cancer cell lines with constitutively active β-catenin but not in the β-catenin-inactive cell line." (PMID 18414679, 2008). "However, whether propofol could regulate the SIRT1 level in cancer further influence stemness and EMT in colon cancer still needs to be further investigated." (PMID 37490168, 2023). "We speculate that SIRT1 drives Snail to promote colon cancer progression, not by provoking a conventional EMT‐related transcriptional repressor function but by inducing transcriptional activator activity of Snail." (PMID 34826187, 2022). "Also in line with our data, a previous qualitative research revealed the regulation of miR-199b on the sirtuin 1/cAMP responsive element binding protein/kisspeptin (SIRT1/CREB/KISS1) signaling pathway and may thus influencing colon cancer." (PMID 33489876, 2020). "Moreover, HINT1 deacetylation by SIRT1 promotes the association of HINT1 with β-catenin, thus inhibiting carcinogenesis through downregulating β-catenin oncogenic activity, which suggests that SIRT1 might serve as a tumor suppressor through deacetylation of HINT1 and β-catenin in colon cancer cells." (PMID 32636443, 2020). "Indeed, we have observed that in colon cancer cell lines and the PDX tumors, SIRT1 protein level was not correlated with the CPT sensitivity." (PMID 26008972, 2015). "Importantly, SIRT1 was absent from the promoters of the genes such as MLH1 and E-cadherin when their promoter DNA is not hypermethylated and the genes are basally expressed in the SW480 colon cancer cells." (PMID 16596166, 2006).
depression (122 papers, 2014 to 2025). "Overexpression of SIRT1 has been linked to anxiety, and depression and brain-specific Sirt1-knockout mice showed reduced susceptibility to depression." (PMID 41304625, 2025). "Consistent with PGC‐1α, other genes, such as NRF2, AMPK and SIRT1 are also associated with mitochondrial biogenesis and depression." (PMID 38334212, 2024). "For example, in a clinical trial where SIRT1 was first identified as a gene associated with major depressive disorder (MDD), SIRT1 was significantly downregulated in blood samples from MDD patients compared to healthy people." (PMID 39684318, 2024). "Previous studies have implicated the hippocampal SIRT1 pathway in chronic stress-induced depression-related phenotypes and abnormal dendritic atrophy." (PMID 38384936, 2024). "At the same time, there was a significant association between single-nucleotide polymorphisms of the SIRT1 gene and major depressive disorder." (PMID 39612426, 2024). "Brain-specific SIRT1 knockout mice exhibit reduced anxiety, while global SIRT1 overexpression increases anxiety and depression susceptibility." (PMID 39275174, 2024). "The increase in NO expression in the brain NO increase was associated with an increase in ICAM-1 and a decrease in SIRT1, but only in the depression state." (PMID 38396638, 2024). "In particular, rs12415800, a gene polymorphism in the SIRT1 gene, has been identified as the first reported genetic variant associated with major depression in the Chinese population through large-scale genome-wide association studies." (PMID 37124257, 2023). "Our study identified a polymorphism, rs12415800, located upstream of the 5′ end of the SIRT1 gene, which is linked to depression and neuroticism." (PMID 37124257, 2023). "Genome-wide association studies have identified the genetic variants of Sirt1 associated with major depression." (PMID 36641776, 2023). "We confirmed that the Sirt1/NF-κB /NLRP3 signaling pathway was associated with luteolin treatment of depression-related dry eye disorder." (PMID 36641776, 2023). "Support for the important of sirtuin-1 in chronic stress resilience includes a significant association between depression and a SIRT1 gene variant identified in a genome-wide sequencing study within a large population of Chinese women." (PMID 37153459, 2023). "The normal expression of SIRT1 is very important for maintaining physiological function, and many diseases are associated with dysregulated SIRT1 expression, such as cancer, neuroinflammation-related diseases, depression, and cardiovascular diseases." (PMID 35677446, 2022). "And a large-scale MDD population study found that the locus causing the risk of major depression was located near the SIRT1 gene, and the SIRT1 expression was significantly downregulated in patients with MDD." (PMID 35664490, 2022). "This study found that there is damage to the microstructure of the white matter neural network fiber bundles in adolescent patients with depression, in which the genetic polymorphism of the SIRT1 gene rs12415800 locus plays an important role." (PMID 36177213, 2022). "In fact, old female mice were more susceptible to LPS-induced depression, and this was accompanied by different Sirt1 activation between males and females." (PMID 35563336, 2022). "This study aimed to explore the correlation between the rs12415800 polymorphism of the silent information regulator 1 (SIRT1) gene and the white matter neural circuit in adolescent patients with depression." (PMID 36177213, 2022). "This study selected adolescent patients with first-episode of untreated depression to explore the relationship between single nucleotide polymorphisms of the SIRT1 gene rs12415800 and the white matter neural network in adolescent depression." (PMID 36177213, 2022). "Sirtuin 1 (SIRT1) has been linked to oxidative stress in neuroinflammation is involved in aberrant mood behavior in response to stressful situations like depression." (PMID 35634375, 2022).